TFE3 (transcription factor binding to IGHM enhancer 3)
Diseases named in the same sentence as TFE3 in open-access papers (continued):
Sharing a sentence is not in itself a finding about the gene and the disease.
tumor (continued). "Immunoistochemically, both benign and malignant tumor cells typically stain positively for S-100, CD68, neuron-specific enolase, CD57, inhibin, calretinin, TFE3, SOX10, and nestin." (PMID 39372871, 2024). "A recent survival analysis of RCC patients with TFE3 overexpression by FISH and immunohistochemistry showed that tumor recurrence and new metastasis were relatively common even at early stages of the disease." (PMID 39206137, 2024). "This disruption not only aligns with the typical cytoplasmic characteristics but also explains the tumor’s positive immunohistochemical staining for TFE3 and wild-type MITF, as lysosomal inhibition activates the transcription factors MITF, TFE3, and TFEB." (PMID 39372871, 2024). "Immunoreactivity of nuclear TFE3 indicated robust CD10, Cathepsin K, P504S, and PAX8 expression in the tumor." (PMID 38953008, 2024). "TFE3 rearrangement was also confirmed by FISH, which showed a split signal in the majority of tumour cells." (PMID 38643139, 2024). "Immunohistochemistry revealed diffusely positive expression of TFE3 and alpha-methylacyl-CoA-racemase (AMACR) in almost all tumor cells." (PMID 39206137, 2024). "Immunohistochemistry showed that the tumor cells were strongly positive for cathepsin-K, HMB45 and TFE3." (PMID 36647137, 2023). "Immunohistochemical staining revealed that the tumor cells were positive for S-100, CD68, SMA, SOX-10, Calretinin, and TFE3." (PMID 37840916, 2023). "In immunohistochemical study, the tumor cells were positively stained with CD31 and CD34 whereas they were negatively stained with TFE3, SMA, S-100, HHV-8 and EMA." (PMID 34757619, 2023). "We previously demonstrated that TFE3 chimeric proteins induce expression of angiopoietin‐like protein 2 (ANGPTL2), a secretory protein that accelerates tumor progression in some cancers, such as lung, breast and colorectal cancers, and osteosarcoma." (PMID 37452654, 2023). "Both benign and malignant tumor cells typically stain positively for S-100, CD68, neuron-specific enolase, CD57, inhibin, calretinin, TFE3, SOX10, and nestin." (PMID 37958362, 2023). "The impact of TFEB knockdown and its family members TFE3 and MITF on PDAC tumor growth has been evaluated in subcutaneous xenografts, but not in orthotopic models, that better recapitulate human disease." (PMID 36746928, 2023). "Immunohistochemistry (IHC) showed tumor cells diffusely expressed TFE3, and fluorescence in situ hybridization (FISH) demonstrated disruption of the TFE3 locus, confirming the diagnosis of Xp11.2 tRCC, the most common subtype of MiTF tRCC." (PMID 37528880, 2023). "In order to further characterize potential functional redundancy of TFEB and TFE3 in the TSC2 KO background, we performed RNA-seq on tumor xenografts grown from WT, TSC2 KO, and TFEB KO, TFE3 KO and double TFEB/TFE3 KO cells." (PMID 36357396, 2022). "It is well established that loss of FLCN induces nuclear localization of the transcription factors TFE3/TFEB and promotes a gene expression program favorable for tumor growth." (PMID 35883484, 2022). "This case report adds to the clinicopathological description of TFE3-rearranged RCC and suggests that larger studies are required to fully elucidate the prognosis of these tumours." (PMID 35530544, 2022). "Our results demonstrated an immune ignorant TIME in the majority of TFE3-tRCCs, characterized by low PD-L1 expression and low CD8 + T-cell infiltration in tumor stroma." (PMID 34489456, 2021).
tumor (continued). "Five neoplasms had different gene fusions including a neoplasm with FUS-CREM gene fusion, two SS with SS18- SSX gene fusion, two ASPS with TFE3-ASPSCR1 gene fusion, and one SFT with immunolabeling for STAT6 indicating a STAT6-NAB2 gene fusion (for details)." (PMID 34350470, 2021). "The tumour cells were positive for S100, SOX-10, and vimentin but negative for pancytokeratin, SMA, desmin, transcription factor E3 (TFE3), and master myogenic regulatory factor (MyoD1) by immunohistochemistry." (PMID 32917245, 2020). "Dataset 1 was obtained from Indiana University, consisting of 50 TFE3-RCC patients and 50 ccRCC patients with matched gender and tumor grade." (PMID 32286325, 2020). "We also found that the basal expression of TFE3 is higher than that of TFEB in ccRCC specimens and tumour cell lines by TCGA and Cancer Cell Line Encyclopedia (CCLE) database." (PMID 33145941, 2020). "In summary, it is indicated that TFE3, like TFEB, is also a potent tumour promotor based on its significant proliferative effect." (PMID 33145941, 2020). "In this study, we collect H&E-stained whole-slide images for 74 TFE3-RCC patients from multiple sources (the largest reported study on TFE3-RCC based on our knowledge) and 74 gender and tumor grade matched ccRCC patients." (PMID 32286325, 2020). "In this study, we collect hematoxylin and eosin- stained histopathology whole-slide images of 74 TFE3-RCC cases (the largest cohort to date) and 74 clear cell RCC cases (ccRCC, the most common RCC subtype) with matched gender and tumor grade." (PMID 32286325, 2020). "Immunohistochemically, the tumor cells were diffusely HMB-45 positive and showed a strong nuclear expression of TFE3." (PMID 31309284, 2020). "Immunohistochemical staining indicated that tumor cells were positive for CD31, CD34, ERG, PCK, FLi-1, TFE-3, and Ki67 (labeling index, 5–15%)." (PMID 33121478, 2020). "By immunohistochemistry, tumor cells were positive for CD31, CD34, ERG, PCK, FLi-1, TFE-3, and Ki-67 (labeling index range, 5–15%)." (PMID 33121478, 2020). "DFSP is composed of cytologically uniform spindled tumor cells, and 0/5 of the studied DFSP samples were TFE3 positive, as similar to SEF samples (0/2)." (PMID 31043173, 2019). "Results showed that the epithelial island regressed after TPF chemotherapy, but the expression levels of TFE3 and HIF-1α evidently increased in the residual tumor island when compared with paired biopsy (P < 0.01)." (PMID 26872381, 2016). "Immunohistochemically, the tumor cells were positive for HMB45, TFE3, and pSTAT3, whereas all other markers tested were negative." (PMID 25621681, 2015). "In addition, SV2B expression was substantially higher than that of SV2A and SV2C in TFE3‐RCC tissues, suggesting that padsevonil inhibited tumor progression in TFE3‐RCC primarily by targeting SV2B." (PMID 41199339, 2026). "These tumour cells are immunohistochemically positive for S-100 protein (supporting the neural origin of granular cell tumour), as well as for neuron-specific enolase, CD68, calretinin, CD57, inhibin, TFE3, SOX, CD59, PGP9.5, and vimentin." (PMID 40256332, 2025). "TFE3 overexpression in P4+TFE3+ CAF enhanced tumor sphere formation in LNCaP/22Rv1 cells through PCYT1A‐mediated PC secretion, whereas dual TFE3 overexpression and PCYT1A knockdown (oeTFE3 + shPCYT1A) in P4+TFE3+ CAF reduced spheres." (PMID 40917018, 2025). "The tumor cells exhibited an endothelial cell phenotype with diffuse strong positivity for CD34, CD31, ERG, and FLi-1, and diffuse and strong nuclear reactivity to TFE3." (PMID 39917171, 2025).
tumor (continued). "Notably, simultaneous interference with TFE3 in P4+TFE3+ CAF and HIF1A in tumor cells more effectively inhibited xenograft tumor growth compared to single‐gene interference." (PMID 40917018, 2025). "Additionally, in this case, tumor cells don’t express CD117, TFE3, HMB45, or SDHB, but express FH and INI1(SMARCB1)." (PMID 41306531, 2025). "To validate the colocalization of STEAP4 and TFE3 in PCa patients, we applied in situ multi‐color immunofluorescence staining using antibodies against COL1A1, STEAP4, and TFE3, and observed STEAP4 and TFE3 double‐positive fibroblasts among the stromal cells within the tumor." (PMID 40917018, 2025). "The stromal specificity of this pathway is underscored by the absence of TFE3/PCYT1A co‐expression in epithelial tumor cells, suggesting CAFs create a lipid‐rich niche that enables tumor cell persistence under ENZ pressure." (PMID 40917018, 2025). "Immunohistochemistry revealed TFE3 (+), MyoD1 (-), Ki67 (8%), Desmin (partial +), S100 (-), SMA (interstitial+), CD56 (weak +), and periodic acid–Schiff (PAS)-positive and amylase-resistant rod-shaped crystals in the cytoplasm of the tumour cells." (PMID 38872175, 2024). "The TFE3-ASPL gene fusion has been shown to upregulate pro-inflammatory cytokines and promote an angiogenic and proliferative microenvironment, that probably confers a unique sensitivity of these tumours to anti-angiogenic agents." (PMID 40171452, 2024). "Of note, in terms of immunohistochemical profile, these PEComa-like neoplasms showed no reactivity for MelanA or HMB45 but were positive for TFE3 and occasionally for SMA." (PMID 38643139, 2024). "The results of fluorescence in situ hybridization (FISH) showed that more than 50% of the tumour cells had red and green signal segregation in the nuclei, indicating that the TFE3 gene was damaged, suggesting nonequilibrium translocation of the TFE3 gene." (PMID 38872175, 2024). "ARID2 knockout (KO) enhanced TFE3-RCC cell migration, proliferation, and tumor growth." (PMID 39727945, 2024). "Regarding molecular rearrangements, among the neoplasms with available data, the SFPQ/PSF::TFE3 fusion was the most frequent genetic alteration found (14 cases, 74%), followed by ASPL/ASPSCR1::TFE3 (3 cases, 16%), RBM10::TFE3 (1 case, 5%), and MED15:TFE3 (1 case, 5%)." (PMID 39410016, 2024). "It has been suggested that the nomenclature for TFE3 translocation PEComa should no longer be used since the pigmented Xp11 tumour nomenclature is more appropriate." (PMID 38291475, 2024). "Tumor-specific signatures were extracted using whole exome sequencing (WES) and RNA sequencing (RNA-seq) data, and the functional consequences were analyzed in a cell line with TFE3 translocation." (PMID 39085357, 2024). "TFE3 nuclear staining can also be observed in PEComa and granular cell tumour but MelanA, HMB45, PS100 and SOX10 are usually positive in these tumours, especially PEComa, which can sometimes share morphology closely resembling ASPS as well as alterations in the TFE3 locus." (PMID 38643139, 2024). "Further single-nucleus-RNA-sequencing revealed that TAM from LP diet-treated MYC-PyMT tumor had higher transcripts for phagolysosome biogenesis, phagocytosis, and endocytosis due to the nuclear translocation and transcriptional regulation of TFEB/TFE3." (PMID 37884533, 2023). "We further find that TFE3 is constitutively localized to nuclei in RCC cells and tumor samples." (PMID 36935008, 2023). "In the tumor without TFE3 gene amplification in this study, multiple signals appeared to be in singly scattered multinucleated giant tumor cells but not in all tumor cells; the cells with multiple signals were larger than ordinary tumor cells." (PMID 36740682, 2023). "In addition, tumours displayed CAMTA1 positivity if they harboured a CAMTA1 fusion and TFE3 positivity in the one tumour harbouring a TFE3 fusion." (PMID 37686662, 2023).
tumor (continued). "The unbiased high-throughput drug screen identified pharmacological targets for TFE3-RCC from an array of known anti-tumor agents but was not directed against specific dysregulated pathways in the tumor." (PMID 37095531, 2023). "GPNMB protein expression by IHC was high in the TFE3-fusion RCC tumor tissues that gave rise to the TFE3-fusion cell lines, but was largely negative in adjacent normal kidney parenchyma." (PMID 37095531, 2023). "This suggests that TFE3 gene rearrangement in renal epithelioid-AMLs is very rare and that being positive for TFE3 protein does not mean that there is TFE3 gene rearrangement in tumor cells." (PMID 36740682, 2023). "Two of these three cases were found to have TFE3 gene amplification in tumor cells despite the absence of split signals." (PMID 36740682, 2023). "The tumor cells showed diffuse positivity for CD10, IFITM1, CD99 and TFE3 (strong nuclear)." (PMID 36707859, 2023). "The tumour for case #154 also displayed positive TFE3 staining despite lacking a TFE3 rearrangement." (PMID 37686662, 2023). "The tumor suppressor FLCN and its binding partner FNIP2 comprise the primary GAP complex activating RagC/D and are accordingly crucial for the phosphorylation of TFEB/TFE3 by mTORC146,50." (PMID 36357396, 2022). "In contrast to the apparent redundancy of TFEB and TFE3 for tumor growth in vivo, in vitro results suggested that single TFEB or TFE3 KO may be sufficient to dampen the phosphorylation of direct mTORC1 substrates (p-4E-BP1 and p-p70S6K)." (PMID 36357396, 2022). "Immunohistochemistry results revealed tumor cells positive for TFE3, but have no consistency in other markers." (PMID 34917511, 2021). "Rescue experiments showed that sunitinib lost its ability to enhance tumor cell metastasis without TFE3." (PMID 33637706, 2021). "Immunohistochemistry results revealed tumor cells diffusely positive for TFE3, but have no consistency in other markers." (PMID 34917511, 2021). "We also found that expression of TFE3 but not TFEB was positively correlated with the levels of PD‐L1 in RCC tumour cell lines by CCLE database." (PMID 33145941, 2020). "It contains 24 TFE3-RCC patients and 24 ccRCC patients, also with matched gender and tumor grade." (PMID 32286325, 2020). "TFE-3 immunohistochemistry (clone MRQ-37, Cell Marque, Rocklin, CA, USA) revealed only a weak-to-moderate nuclear staining, which is not characteristic of a TFE-3 translocated tumor." (PMID 31309284, 2020). "Only a small subset of tumor cells with minimal separation of the 5′TFE3 and 3′TFE3 probe signals were detected, not meeting established cut-off values." (PMID 31309284, 2020). "Immunostaining of TFE-3, INL1 and Ki67 was positive in the tumour cells of two patients." (PMID 32085747, 2020). "In our study, calcifications were detected in 50% of Xp11.2/TFE3 RCC cases and were more common in Xp11.2/TFE3 RCC than in ccRCC or pRCC; the calcifications appeared in a circular arrangement around or within the tumour, which was in agreement with the findings of a previous report." (PMID 31892340, 2019). "The PEComa-like tumor showed strong Melan-A and weak transcription factor E3 (TFE3) protein expression but no TFE3 gene rearrangement." (PMID 30876389, 2019). "Moreover, when TFEB and TFE3 were knocked down in the cancer cells, the favorable interaction between MTX and 3,4‐DC leading to stronger tumor growth reduction than with MTX alone was lost." (PMID 31609086, 2019). "Immunohistochemistry showed strong positivity within tumor cells for Vimentin and Melan-A, weak but diffusely positive for TFE3 protein, while HMB45 was negative." (PMID 30876389, 2019). "Immunohistochemistry results revealed tumor cell positive for TFE3, but have no consistency in carbonic anhydrase IX, CD117, Ki67, CK8/18 AE1/AE3 and so on." (PMID 29901594, 2018). "The tumor displays cytoplasmic ALK and nuclear TFE3 immunostaining." (PMID 29053609, 2017).
tumor (continued). "Although TFE3-negative EHEs demonstrated small tumor sizes, they were more likely to present multiple lesions in the primary tumor site whereas TFE3-positive EHEs exhibited a single lesion (P = 0.0359)." (PMID 26840265, 2016). "In this case, approximately 15 % of the tumor cells showed split signals, and a copy number gain of TFE3 gene was also observed in some tumor cells with or without translocation (3 to 5 signals per nucleus)." (PMID 27733182, 2016). "These tumours characteristically do not show expression of TFE3 on immunohistochemical analysis and have other peculiar morphologic and immunohistochemical features." (PMID 26837430, 2016). "Tumours were confirmed imunohistologically by positive reaction for CD10, P504S and TFE3." (PMID 24991210, 2014). "Lesion biopsy and the use of antibodies against TFE3 in all RCC, with emphasis on young adults, may be necessary to determine the biologic nature and incidence of this tumour." (PMID 24991210, 2014). "TFE3 RCC presents both papillary/alveolar architecture and tumor cells with a clear cytoplasm." (PMID 24676409, 2014). "The tumor cells showed patchy immunoreactivity for HMB-45 in a cytoplasmic and membranous pattern, patchy moderate immunoreactivity for progesterone receptor, diffuse nuclear staining for TFE3 and patchy but strong, membranous positivity with C-kit/CD117." (PMID 24735727, 2014). "Furthermore, in cells expressing TFE3, inhibition of MET using siRNA or a small molecule MET inhibitor impaired tumor growth." (PMID 19146682, 2009). "Thus, our study reveals a novel mechanism by which D-mannose controls TFE3-mediated activation of lysosomal function and VEGFR2 degradation to inhibit angiogenesis and tumor growth in CRC, providing an experimental basis for the potential application of D-mannose in the clinical treatment of CRC." (PMID 40259886, 2025). "Further studies revealed that D-mannose inactivates GSK3β, enhances the nuclear translocation of TFE3, upregulates the transcription levels of lysosomal biogenesis-related genes, and promotes lysosomal-mediated degradation of VEGFR2, thereby inhibiting angiogenesis and tumor growth in CRC." (PMID 40259886, 2025). "By IHC and immunoblotting, STP tumor cells showed strong expression of nuclear TFE3, the canonical TFE3 target GPNMB, as well as expression of melanocytic and lysosomal markers (PMEL, MelanA and Cathepsin K) commonly upregulated in human MiT/TFE-related neoplasms." (PMID 41044182, 2025). "Importantly, this case occurred in a tumor exhibiting transcription factor E3 (TFE3) immunopositivity without the canonical TFE3 gene translocation, highlighting a specific diagnostic challenge." (PMID 41275415, 2025). "The tumor differs from other RCC types in the presence of various translocations on chromosome Xp11.2, resulting in a gene fusion involving TFE3; there are at least six possible fusion types which are currently described as TFE3-rearranged RCC, the predominant subtype." (PMID 38953008, 2024). "TFE3-rearranged-RCC exhibited a significant higher recurrence rate compared to ccRCC (50% vs 18.8%) and multivariate analysis revealed that TFE3 rearrangement, along with tumor size and metastasis, was an independent prognostic factor for recurrence (HR = 4.6; 95% CI 1.1-21.2; p = 0.05)." (PMID 39470841, 2024). "The tumour stains for TFE3 on immunohistochemistry; however, the same is not specific to ASPS." (PMID 40171452, 2024). "Finally, the group mainly composed of NONO::TFE3 and SFPQ/PSF::TFE3 fusion neoplasms featured a low expression of angiogenesis modules and moderate enrichment of E2F signaling." (PMID 39410016, 2024). "The tumour cells were also positive for GATA3, E-cadherin, Pax-8, Succinate dehydrogenase B (SDHB) and Fumarate hydratase (FH), and negative for vimentin, Carbonic anhydrase 9 (CA9), CD10, P504s, CK20, TFE3, TFEB, HMB45, ALK and Forkhead box protein I1 (FOXI1)." (PMID 36816543, 2023).